CDH24 (cadherin 24)
Description:
Cadherins are calcium-dependent cell adhesion proteins. They preferentially interact with themselves in a homophilic manner in connecting cells; cadherins may thus contribute to the sorting of heterogeneous cell types. Cadherin-24 mediate strong cell-cell adhesion.
Synonyms: CDH11L
Tractability: Antibody: UniProt places it where antibodies can reach, with high confidence; its Gene Ontology location is reachable by antibodies, with high confidence; UniProt predicts a signal peptide or a membrane-spanning region.
Gene: Protein-coding gene on chromosome 14 (23,047,062 to 23,057,538, reverse strand). Ensembl gene ENSG00000139880.
Subcellular location: Cell membrane
Subcellular location (Human Protein Atlas): Cytosol; Vesicles
Pathways (Reactome):
Cell-Cell communication: Adherens junctions interactions; CDH11 homotypic and heterotypic interactions
Gene Ontology:
Molecular function: calcium ion binding; beta-catenin binding; cadherin binding
Biological process: cell-cell adhesion; adherens junction organization; calcium-dependent cell-cell adhesion; cell migration; cell morphogenesis; cell-cell adhesion mediated by cadherin; cell-cell junction assembly; cell adhesion; homophilic cell-cell adhesion
Cellular component: cell-cell junction; adherens junction; catenin complex; plasma membrane; membrane
Genetic constraint (gnomAD): Loss-of-function variants: 59 observed, 63.95 expected, observed/expected ratio (o/e) 0.92, 90% interval 0.75 to 1.15. The upper end of that interval is the gene's LOEUF score, 1.15, which puts it in group 5 of 6, group 1 being the genes least tolerant of losing a copy. Missense variants: 957 observed, 1,022.9 expected, observed/expected ratio (o/e) 0.94, 90% interval 0.89 to 0.99. Synonymous variants: 438 observed, 440.14 expected, observed/expected ratio (o/e) 1, 90% interval 0.92 to 1.08.
Homologues: Orthologues: chimpanzee CDH24 (98% identical), macaque CDH24 (98% identical), pig CDH24 (96% identical), guinea pig CDH24 (95% identical), rat Cdh24 (94% identical), dog CDH24 (94% identical), mouse Cdh24 (93% identical), rabbit CDH24 (86% identical), tropical clawed frog cdh24 (63% identical), zebrafish cdh24b (54% identical), zebrafish cdh24a (50% identical). Paralogues in human: CDH11 (56% identical), CDH8 (53% identical), CDH18 (51% identical), CDH20 (50% identical), CDH7 (50% identical), CDH10 (48% identical), CDH6 (48% identical), CDH9 (48% identical), CDH12 (47% identical), CDH22 (46% identical), CDH19 (40% identical), CDH5 (38% identical), and 21 more.
Diseases named in the same sentence as CDH24 in open-access papers:
CDH24 is named in the same sentence as 4 diseases in open-access papers, as found by Europe PMC text mining. Sharing a sentence is not in itself a finding about the gene and the disease. The quoted sentences say what the papers report.
neuroblastoma (1 paper, 2017). Neuroblastoma (NB) is the most common solid, extracranial childhood tumor. "Specifically, we found that, for MYCN amplified neuroblastoma, pairwise expression of ACVR2B or anaplastic lymphoma kinase (ALK) with GFRA3, GFRA2, Cadherin 24, or with one another provided the strongest hits." (PMID 28871274, 2017).
CDH24 also shares sentences with these, for which no sentence is quoted: autism (1 paper); lung carcinoma (1); tumour (1).